STAT3 (signal transducer and activator of transcription 3)
Diseases named in the same sentence as STAT3 in open-access papers (continued):
Sharing a sentence is not in itself a finding about the gene and the disease.
infection (continued). "Meanwhile, cells-treated with 300 μg/mL arginine medium ruduced the phosphorylation and gray values of p-JAK2 and p-STAT3 after infection with FAdV-4, compared with FAdV-4 infection cells (P < 0.05)." (PMID 35590365, 2022). "We next analyzed the protein-protein interaction network even further and demonstrated that the infection related proteins STAT3, AKT1, MAPK9, MAPK14, and CREBBP had the highest degree of connectivity among DAPs." (PMID 36262184, 2022). "In juvenile STAT3 mutant zebrafish, a dramatic alteration in the number of genes involved in immune and infection response, skeletal development, somatic cell growth and downregulated expression of the collagen gene family was observed." (PMID 35505881, 2022). "Several studies have shown that steE can promote IL-10 production via the activation of STAT3 signaling and metabolic and physiological environment reprogramming for Salmonella in B cells, changing it from an anti-inflammatory to an infection state." (PMID 35909683, 2022). "Infections are a common feature in STAT3 GOF, but infection susceptibility is complicated by the need for immune suppression to control autoimmune symptoms." (PMID 36843887, 2022). "We further discovered that B7-H4−/− infection impairs the JAK2/STAT3 pathway, contributing to dDC dysfunction." (PMID 35505420, 2022). "We performed time-course experiments to compare the STAT3 phosphorylation at early time-points after infection." (PMID 35910598, 2022). "On the other hand, STAT3 was only activated during infection with the parental P. aeruginosa strain." (PMID 35508983, 2022). "Infection of Apc Min/+ mice with ETBF induced selective activation of Signal transducer and activator of transcription 3 (STAT3) with CRC characterized by Th17 responses." (PMID 37206892, 2022). "Herein, there was a significant increase in the expression of phosphorylated STAT1 and STAT3 in mouse lungs after H9N2 infection." (PMID 33968006, 2021). "In contrast, there was a significant reduction or failure in activation of type 2-related chemokines/cytokines (Cxcl12, Ccrl1, Il4, Il23a) and signature markers (Stat3, Stat5b, Stat6, Mrc1, Ahr) during infection." (PMID 34320039, 2021). "Surprisingly, in contrast to the rapid activation of NF-κB at one hour, STAT3 activation was delayed post-infection and reached its peak at 24 h." (PMID 34419066, 2021). "Western blot results showed that the expression of NICD and the phosphorylation level of STAT3 were obviously decreased from LV-Notch1-shRNA infection group in IL-9 treated-astrocytes, compared to the LV-ctrl group." (PMID 33971906, 2021). "Treatment with TTI-101 was used to inhibit STAT3 activity, and treatment with benznidazole was used to clear the infection to evaluate the effect of STAT3 if the parasites were removed." (PMID 34504808, 2021). "Our results demonstrated an early induction of p-NF-κB-P65 (Ser536) at 1 h, whereas p-STAT3 (Y705) was delayed and increased at 24 h time point, following infection with H. pylori strain 7.13 or J166." (PMID 34419066, 2021). "In Vero cells, STAT1 and STAT3 phosphorylation level similarly increased until 24 h culture in medium containing 2% FBS after mock-infection and HCoV-OC43 infection." (PMID 34835005, 2021). "For example, a recent study indicated that STAT3 is phosphorylated as a result of infection with Rift Valley fever virus (RVFV)." (PMID 34070281, 2021). "They found an expected high increase in p-STAT3 in the infected B6 mice, but the p-STAT3 response was weak in NK cells from NKIl10R− mice at 72 h post-infection." (PMID 35053151, 2021). "In an ongoing infection, STAT3 is activated during the innate immune response, primarily through type I IFNs." (PMID 33767335, 2021). "The results showed an increase of p-NF-κB after 1 h infection and 24 h for p-STAT3 in the nuclear fraction after H. pylori infection." (PMID 34419066, 2021).
infection (continued). "Interferon Regulatory Factors activate STAT1, STAT2, and STAT3 that stimulate the innate and acquired immune responses, mediate cellular responses to interleukin, and regulate inflammatory responses to infection." (PMID 34207861, 2021). "To gain a better understanding of the signaling mechanism by which SpvB regulates hepcidin expression, we examined both the BMP/SMAD and JAK/STAT3 pathways in the liver of WT-infected and ΔspvB-infected mice at 3 days post-infection." (PMID 33475464, 2021). "STAT1 and STAT3 phosphorylation occurred consistently in Vero cells during the mock infection culture as we expected." (PMID 34835005, 2021). "The relative quantity (ΔCq) values of each transcript were normalized with STAT3 transcript, which varies relatively less in infection conditions and moderate levels, and the results were evaluated." (PMID 33597825, 2021). "MAPKs and STAT3 are the key signaling regulators in modulating the production of pro-inflammatory mediators and cytokines during infection." (PMID 34681270, 2021). "A major immune function of ZDHHC19 is to facilitate activation of STAT3 upon cytokine stimulation, which is important for immune signaling in infection and inflammation." (PMID 34442377, 2021). "KSHV de novo infection-induced NF-κB and STAT3 activation ensures cell growth, cell survival and KSHV latency." (PMID 33182552, 2020). "In E. coli pneumonia, STAT3 can promote neutrophil recruitment and limit both infection and lung injury." (PMID 32802131, 2020). "The finding that recombinant SteE can replace infection- or transfection-delivered SteE shows that the proteins required for STAT3 phosphorylation are already present in the GSK3 complex." (PMID 31862381, 2020). "Mounting evidence has revealed that transient induction of inflammation by NF-κB and STAT3 in response to injury or infection is essential to activate immune responses." (PMID 33182552, 2020). "To test this, we screened an array of tyrosine-kinase inhibitors during infection of cells with steE-mutant Salmonella expressing SteE:HA and monitored STAT3 phosphorylation." (PMID 31862381, 2020). "De novo infection by these viruses induces rapid NF-κB and STAT3 activation and creates a favorable environment for virus entry into host cells and viral latency." (PMID 33182552, 2020). "In our opinion, it is reasonable to further describe BKPyV life cycle and STAT3 pathway (upstream and downstream) in our 3D infection model to identify more interesting targets, for example other inflammatory interleukins." (PMID 32588533, 2020). "In this review, we will discuss the mechanisms that are specifically involved in NF-κB and STAT3 activation during de novo infection and latency by KSHV, EBV and HTLV-1." (PMID 33182552, 2020). "STAT3 mutations disrupt TH17 generation in vitro and in vivo and highlight the importance of STAT3 in TH17 differentiation and TH17 effector role in infection of HIES patients and other immune-mediated diseases." (PMID 33271763, 2020). "In both infections, STAT3 TKO mice also had a significant reduction in IFN-γ-IL-21+ Teff, supporting reports that STAT3 signaling promotes IL-21 expression." (PMID 32634740, 2020). "oprC deficiency downregulates P. aeruginosa virulence, alleviates infection, and improves inflammation via reduced pyroptosis and STAT3/NF-κB phosphorylation." (PMID 32849593, 2020). "In our study, we revealed that TgROP18 activated the IL20R-JAK/STAT3 pathway for anti-infection against T. gondii, and mainly played a role in early infection." (PMID 32767999, 2020). "Infection-induced STAT3 phosphorylation in THP-1 cells were diminished after silencing TLT2 followed by H37Rv or BCG infection, suggesting that STAT3 was required for TLT2 function on cytokine secretion." (PMID 33042115, 2020).
infection (continued). "The role of STAT3 in the epithelial compartment is complex, it is important for inducing return to homeostasis following acute infection, while at the same time it involves the induction of cytokines and chemokines expression." (PMID 33363184, 2020). "Mechanistically, T-bet, and not STAT1 or STAT4, regulated IFN-γ production by T cells; and T cell-intrinsic expression of STAT3, Bcl6, and Blimp-1 each regulated T-bet expression during the peak of infection." (PMID 32634740, 2020). "Exposure of DCs to this infection results in an increased release of IL-6 and IL-10 with STAT3 phosphorylation." (PMID 33028328, 2020). "Although studies have shown that acute induction of inflammation by NF-κB and STAT3 in response to infection eliminates or limits pathogen spread, chronic inflammation driven by NF-κB and STAT3 activation create favorable environments for EBV, KSHV and HTLV-1." (PMID 33182552, 2020). "STAT3 targets were upregulated at the early stage of infection and then mostly depressed at 24 hpi as the infection proceeded, indicating that STAT3 activation in glial cells was under tight control during infection." (PMID 31575039, 2019). "On the other hand, both un-phosphorylated and phosphorylated STAT3 competed with STAT1 for KPNA1 binding upon infection, leading to repressed ISG expressions." (PMID 31575039, 2019). "Tyrosine (Y705) phosphorylated STAT3 (p-STAT3) was detectable in lysates of these NK cells at both time points after infection, though more p-STAT3 was observed at 72 hpi." (PMID 31552035, 2019). "H. felis infection led to activation of STAT3 in the stomach of WT and Myd88−/− mice after 25 and 47 weeks of infection." (PMID 31065023, 2019). "High IL6 level linked with phosphorylated STAT3 level, poor liver function, variceal severity, and patients' mortality in cirrhotic patients caused by HBV‐ and HCV‐infection." (PMID 31219249, 2019). "Immunofluorescence (IF) assay showed that in contrast to the mock infected T98G cells in which STAT3 was detected in both the cytoplasm and nucleus, STAT3 was mainly detected in the nucleus of the infection group." (PMID 31575039, 2019). "Intriguingly, we found that besides the degradation of KPNA1, another indispensable factor that restricts host antiviral response was the competitive binding of STAT3 to KPNA1 during infection." (PMID 31575039, 2019). "Under inflammatory conditions, hepcidin is transcriptionally induced by IL-6/STAT3 signaling and promotes hypoferremia, an innate immune response to infection." (PMID 31295319, 2019). "Taken together, our data suggested the role of STAT3 in maintaining the balance of inflammation and antiviral responses in the central nervous system (CNS) upon infection." (PMID 31575039, 2019). "Our data demonstrated that IL-10 and the STAT3 gene were upregulated in the lung from IL-17–/– PCP mice compared with WT-PCP mice after 2 wk of infection with Pneumocystis." (PMID 31582901, 2019). "PIAS3 and SOCS1, two regulators that had been reported to restrict the expression of STAT3 target genes, showed a significant increase of the expression upon infection." (PMID 31575039, 2019). "Several studies pointed that M.tb successfully engages activators of IL-10 transcription such as STAT3 and ReIB during infection to abolish the protective response mounted by the host and ensures its survival and persistence." (PMID 31921181, 2019). "STAT3 inhibitors and IL-15C complexes are thus, respectively, attractive candidates for treatment of these infections." (PMID 31552035, 2019). "The phosphorylated and un-phosphorylated STAT3 competed with STAT1 for binding to the decreased KPNA1 post infection and repressed downstream ISG expression." (PMID 31575039, 2019). "According to this model, miR-122 is responsible for restricting STAT3 phosphorylation to a low level in normal hepatocytes, which enables a robust innate immune defense upon infection." (PMID 30735121, 2019).
infection (continued). "Inflammatory induction of hepcidin involves IL-6/STAT3 signaling and is considered to be protective during infection as an innate immune response that deprives bacteria from iron, an essential nutrient." (PMID 31295319, 2019). "STAT3 knockdown alleviated the repressed type I IFN-mediated antiviral response upon infection and led to decreased viral replication." (PMID 31575039, 2019). "Another new finding of this study is that EBV, in correlation with STAT3 activation, reduced autophagy during the first phases of infection of B cells, and this effect was also counteracted by quercetin." (PMID 31547402, 2019). "We infected T98G cells with EV71 and, consistent with the mice astrocytes, phosphorylation of STAT3 at both sites was also observed post infection." (PMID 31575039, 2019). "Several studies have demonstrated that STAT3 was indispensable for Tfh and Tfr cell differentiation by inducing the expression of Bcl-6 during immunization or infection." (PMID 31382877, 2019). "In the current study, we found that CA16 infection significantly increased the phosphorylation level of STAT3 and the expression of NF-κB, together with the increase of PERK expression." (PMID 30186868, 2018). "STAT3 has been previously reported to be involved in regulating inflammatory mediators and subsequent neutrophil trafficking during infection, where inhibition of STAT3 reduced neutrophil chemokines and recruitment." (PMID 30473701, 2018). "Other viruses have developed alternative strategies to impair STAT3 function, such as manipulating its subcellular localization during infection." (PMID 29543893, 2018). "First, the role of STAT3 expression in myeloid cells in the control of infection with M. tuberculosis was examined using stat3fl/fllysm cre mice." (PMID 29338039, 2018). "The daytime point of infection coincides with high levels of STAT3 protein and of clock genes Per1, Per2 and Nr1d1 mRNAs, and was chosen to deduce a possible LPS-induced decrease of their levels." (PMID 30265676, 2018). "Respiratory syncytial virus can activate STAT3 via IL-6, and the activation is necessary for the viral early gene activation and successful infection of epithelial cells." (PMID 32201498, 2018). "We report here that stat3fl/flysm cre mice show reduced M. tuberculosis load in lungs and spleens, indicating that STAT3 expression in myeloid cells is detrimental for the control of infection with M. tuberculosis." (PMID 29338039, 2018). "RNA-based next generation sequencing revealed an up-regulation of Il10, Il10rα and further genes involved in IL-10 downstream signaling, including Jak1, Socs3 and Stat3 in the brain upon infection." (PMID 29666403, 2018). "As the infection progresses, STAT3 activity is suppressed to a degree that inversely correlates with the pathogenicity of each IAV strain." (PMID 29543893, 2018). "Altogether, STAT3 signalling in myeloid cells is deleterious in the control of infection with M. tuberculosis." (PMID 29338039, 2018). "On the other hand, infection of EBV results in the activation of STAT3 and NF-κB signal cascades in target epithelial cells, which induces increased expression of inflammatory cytokines including IL-6 and COX-2." (PMID 29844870, 2018). "The phosphorylation of STAT1 and STAT3 in NKLAM-KO lungs was lower than in WT lungs at 24 hours post-infection." (PMID 29518136, 2018). "Upon ocular infection of Stat1−/− ΔNTD mice that succumb to CNS-localized infection, active STAT3 and IL-6 drive inflammation in the corneal epithelium before a heightened antiviral and pro-inflammatory response develops in the brainstem." (PMID 30167845, 2018). "We studied the role of STAT3, a major regulator of immunity, in the control of the infection with M. tuberculosis." (PMID 29338039, 2018). "Human metapneumovirus (hMPV) infection prevents the nuclear translocation of STAT3 in a cytokine-specific manner, as this was only observed following stimulation with IL-6 and not in case of interleukin 22 (IL-22)." (PMID 29543893, 2018).
infection (continued). "We found that Types I,II,III tachyzoites infection of cells all affected nuclear localization of NFκB1 and STAT3." (PMID 28904337, 2017). "Later in infection, the STRING analysis indicated a shift in the response to S. Typhimurium infection to gene expression patterns associated with STAT3 activation." (PMID 28742135, 2017). "In our previous experiments, we found that selective infection of RGCs with AAV2.Stat3 construct was sufficient to promote axonal growth in the crushed optic nerve." (PMID 29234527, 2017). "The level of phosphorylated STAT3 increased after infection with HCVcc in Huh7 cells; however, overexpression of GRIM-19 did not reduce the increased phosphorylation of STAT3." (PMID 28443075, 2017). "Cells infected with S. Typhimurium showed a marked activation of STAT3, particularly late in infection." (PMID 28742135, 2017). "STAT1, STAT2, and/or STAT3 tyrosine phosphorylation has been demonstrated by others to occur in fibroblast cells or macrophages at various times following infection with TC-MCMV." (PMID 28182772, 2017). "In conjunction with the general profile of the B cell response to infection, we analyzed the stage-specific cell surface markers of infected B cells in the absence or presence of STAT3." (PMID 27486189, 2016). "We provide the first evidence that STAT3 expression is needed for murine gammaherpesvirus 68 to establish latency in primary B cells during an active immune response to infection." (PMID 27486189, 2016). "To address this question, we investigated the role of STAT3 signaling within human primary macrophages during the 24 first hours of infection with M. tuberculosis." (PMID 27384401, 2016). "Inhibition of STAT3 signaling during infection led to an increase of the inflammatory cytokine secretion, IL-6 (26 fold) and TNF-α (5 fold), compared to control infected macrophages." (PMID 27384401, 2016). "Immunoblotting showed that after PAO1 infection, the levels of total and phosphorylated STAT3 were increased in the Ezrin-silenced MH-S cells, indicating that Lyn indeed regulates the STAT3 activation by binding Ezrin." (PMID 29263906, 2016). "Although IL-6 and IL-10 were both secreted in the first hours of infection, IL-10 mainly mediates the activation of STAT3 signaling in infected macrophages." (PMID 27384401, 2016). "To avoid any bias or misinterpretation due to hMΦ stress following M. tuberculosis uptake, we analyzed the gene expression 24 hours post-infection, when STAT3 is still activated." (PMID 27384401, 2016). "The number of M. tuberculosis Colony Forming Units (CFUs) that was taken up 4 hours after infection was similar for hMΦ silenced for STAT3 (siSTAT3) and for hMΦ transfected with control siRNA (scramble)." (PMID 27384401, 2016). "The results showed that H9N2 infection increased phosphorylated STAT3 in the nuclear fraction, while treatment with E804 significantly reduces the nuclear translocation." (PMID 26732368, 2016). "In the early stage of infection, STAT3 also strongly represses the production of inflammatory cytokines such as IL-6, while enhancing secretion of anti-inflammatory IL-10." (PMID 27384401, 2016). "To avoid any misinterpretation due to the macrophage stress induced by M. tuberculosis uptake, we observed the consequence of STAT3 silencing 24 hours post-infection." (PMID 27384401, 2016). "The up-regulation of both TNF-α and IFN-γ mRNA suggests that STAT3 represses inflammatory cytokine production at the transcriptional level, limiting acute inflammation at the site of infection." (PMID 27384401, 2016). "In all, the data suggested that infection-induced induction of Bcl-2 was predominantly mediated through STAT-3." (PMID 27826299, 2016). "In summary, EBV- and KSHV-infection mediated activation of STAT3 can be divided into very early and late phases." (PMID 27458446, 2016). "STAT3 was found to be highly phosphorylated 3 hours post-infection and the level of its phosphorylation was significantly maintained for 24 hours." (PMID 27384401, 2016).